PDCD1 (programmed cell death 1)
Diseases named in the same sentence as PDCD1 in open-access papers (continued):
Sharing a sentence is not in itself a finding about the gene and the disease.
colon carcinoma (34 papers, 2017 to 2025). "Taking into consideration our results indicating that colon tumors from AA patients appear to have an impaired cytotoxic tumor environment, we examined the expression of immunotherapy targets Programmed cell Death-1 (PD-L1) and cytotoxic T-lymphocyte-associated protein 4 (CTLA-4) in our samples." (PMID 32983990, 2020). "A subpopulation of Cd8−/Cd4− and Pdcd1+/ll17a+ T cells earmarks these tumors, which likely represent the counterpart of γδ+ T cells observed in colitis-like colon cancers." (PMID 38902475, 2024). "In patients with stage II to stage III colon cancer, increased PDCD1 expression in cancer tissues hinders T cell immune responses to tumors." (PMID 39640266, 2024). "In this report, we present a rare case where a patient with MSS colon cancer that carried a somatic POLE mutation and hypermutated phenotype was treated with the programmed cell death 1 (PD-1) receptor inhibitor pembrolizumab." (PMID 37239414, 2023). "Two immune checkpoint inhibitors (ICIs) that target programmed cell death-1 (PD-1) have been FDA-approved for the treatment of patients with colon cancer exhibiting high microsatellite instability (MSI-H) or DNA mismatch repair (MMR) deficiency (dMMR)." (PMID 35203508, 2022). "Use of this compound in monotherapy or in combination with an anti-programmed cell death 1 (PD-1) antibody in mouse models of colon cancer inhibits tumor growth at well-tolerated doses." (PMID 34886882, 2021). "We selected immune checkpoints common in colon cancer therapy for analysis, finding that CD274, PDCD1, and HAVCR2 were positively correlated with the risk score." (PMID 34840571, 2021). "Additionally, the phagocytic ability of tumor-associated macrophages to tumor cells was negatively correlated with PDCD1 expression in colon cancer." (PMID 39052013, 2024). "In our study, we observed differences in the expression levels of various immune checkpoint molecules, including PDCD1, CD86, and CD47, between the high and low-risk groups, indicating that colon cancer patients in the two risk groups may exhibit different responses to ICIs." (PMID 38188686, 2023). "In contrast, CD27, CD276, LAG3, LGALS9, PDCD1, and TMIGD2 showed a highly enriched trend of expression with RFX1 in colon cancer." (PMID 41425715, 2025). "The AIM2 activation was associated with an increased anti-tumor response after the anti-Programmed Cell Death 1 (PD-1) blockade, an effect that was attenuated in AIM2 knockout mice with colon cancer." (PMID 40002808, 2025). "In human colon cancer patients, the expression levels of STAT1, IRF2 and PDCD1 are positively correlated in tumor-infiltrating myeloid cells." (PMID 38995014, 2024). "In colon cancer patients, the expression levels of STAT1, IRF2 and PDCD1 are positively correlated in tumor-infiltrating myeloid cells." (PMID 38995014, 2024). "In addition to SMC1A in the “hot” T‐cell inflammatory microenvironment of colon cancer, SMC1A also positively correlates with the immune checkpoint genes CD274, CTLA4, and PDCD1 in colon adenocarcinoma (COAD) samples." (PMID 37096492, 2023).
pancreatic cancer (30 papers, 2017 to 2024). "We have recently shown that OBP-702 enhanced the anti-tumor efficacy of anti-programmed cell death 1 antibody (anti-PD-1 Ab) in a syngeneic mouse model of pancreatic cancer via the enhancement of ICD and CD8+ T cell infiltration into tumors." (PMID 38745748, 2024). "Several immune checkpoints, including TNFSF4, ICOS, CTLA4, and PDCD1, have been identified as playing crucial roles in the progression of pancreatic cancer." (PMID 37753069, 2023). "Approximately 40% to 70% of CD8A+ T lymphocytes co-expressed PDCD1 and/or HAVCR2 in both IF and TC, independently of the neoadjuvant chemotherapy, suggesting that T cytotoxic lymphocytes are exhausted in the pancreatic cancer microenvironment." (PMID 32645996, 2020). "RNA-sequencing (RNA-seq) of pancreatic tumor lysates and principal component analysis revealed that KC;iASPPΔ8/Δ8 pancreata bear closer resemblance to KC than KPC pancreata and express greater Cd3, Cd4, Itgae, Pdcd1, Il10, Ccl5, Osm, and Cd274, reflective of an immunosuppressive stromal reaction." (PMID 36746936, 2023).
Hodgkins lymphoma (28 papers, 2015 to 2025). A heterogeneous group of malignant lymphoid neoplasms of B-cell origin characterized histologically by the presence of Hodgkin and Reed-Sternberg (HRS) cells in the vast majority of cases. "The programmed cell death-1 (PD-1) pathway has emerged as a highly relevant immune checkpoint pathway in a number of hematologic malignancies, particularly Hodgkin’s lymphoma." (PMID 28018601, 2016).
triple-negative breast carcinoma (28 papers, 2018 to 2025). An invasive breast carcinoma which is negative for expression of estrogen receptor (ER), progesterone receptor (PR), and human epidermal growth factor receptor 2 (HER2). "While the immune checkpoint inhibitor (ICI) anti-programmed cell death 1 (PD-1) pembrolizumab has demonstrated efficacy in triple-negative breast cancers (TNBCs), its benefit in HR + subtypes is limited." (PMID 41153058, 2025). "The SNP of PDCD1, including rs11568821 and rs2227981 was a prognostic marker in a triple-negative breast cancer." (PMID 37608927, 2023). "The available evidence suggests that combination immunotherapy using programmed cell death-1 (PD-1) or programmed cell death-ligand 1 (PD-L1) inhibitors may be a promising treatment option for metastatic triple-negative breast cancer (mTNBC)." (PMID 39512498, 2025). "Chemoimmunotherapy with anti-programmed cell death 1/ligand 1 and cytotoxic chemotherapy is a promising therapeutic modality for women with triple-negative breast cancer, but questions remain regarding optimal chemotherapy backbone and biomarkers for patient selection." (PMID 37344474, 2023). "Similarly, the PFS of patients with advanced triple-negative breast cancer treated with PDCD1/CD274 inhibitors combined with chemotherapy was longer than those treated with chemotherapy alone." (PMID 37988189, 2023).
ovarian carcinoma (27 papers, 2015 to 2025). A malignant neoplasm originating from the surface ovarian epithelium. "For instance, PDCD1 upregulation in SKCM was associated with better overall survival while showing limited prognostic value in ovarian cancer." (PMID 40149458, 2025). "According to our best knowledge, only two studies have assessed the potential association between PDCD1 polymorphisms and ovarian cancer." (PMID 33519815, 2020). "Alternatively, ovarian cancer-associated DC block T-cell proliferation by a programmed cell death-1- (PD-1-) dependent mechanism." (PMID 26491691, 2015). "Expression profiling showed differential PDCD1 expression in tumor versus normal tissues, correlating with improved survival in skin melanoma but limited value in ovarian cancer." (PMID 40149458, 2025). "The combination therapy of DNMTi and histone deacetylase inhibitors (HDACi) synergistically increases reexpression of silenced ERVs in cancer cells and increases sensitivity to the anti-programmed cell death 1 (PD-1) therapy in lung and ovarian cancers." (PMID 32881981, 2020). "We analyzed the expression levels of the checkpoint receptors in the three ovarian cancer subtypes responsible for decreasing T cell bioactivity, including PDCD1 (PD1), CTLA4, LAG-3, and TIM-3." (PMID 33282564, 2020). "In particular, therapy aimed at the programmed cell death 1 (PD-1) and the cytotoxic T-lymphocyte associated antigen 4 (CTLA-4) pathways are currently being studied in numerous clinical trials in ovarian cancer." (PMID 31091744, 2019). "In another study, the SASP secretion of IL‐1β, IL‐8 and CXCL10 induced by cisplatin and irinotecan renders ovarian cancer responsive to programmed cell death 1 (PD‐1) treatment, triggering the activation of CD8+ T cells and enhancing dendritic cell infiltration." (PMID 39270064, 2024). "In vitro overexpression of Pdcd1 could induce apoptosis in the human SKOV3 ovarian cancer cell line and significantly strengthened cisplatin-induced apoptosis." (PMID 35190965, 2022). "Meanwhile, these cells also positively expressed T cell exhaustion markers, including LAG3 and PDCD1, indicating that the CD8+ T cells are exhausted after initial activation in ovarian cancer." (PMID 35935940, 2022).
prostate carcinoma (27 papers, 2016 to 2025). A carcinoma that arises from epithelial cells of the prostate gland. "An ARG, known as NKX2-3 demonstrates overexpression in prostate cancer patients, and is associated with poor overall survival, lymph node metastasis and reduced capacity of PDCD1 inhibitors." (PMID 35317831, 2022). "One of the strategies for prostate cancer immunotherapy is using PDCD1/PD-1 (programmed cell death 1) inhibitors." (PMID 35317831, 2022). "Another study found that high CDK12 levels was associated with increased expression of immune checkpoint factors PDCD1 and CTLA-4 in prostate cancer, supporting the concept of combining CDK12 inhibitors with immune therapy." (PMID 40163908, 2025). "Since upregulated programmed cell death 1 (PD-1) and/or CTLA4 often co-occur with other IEMs, these results provide a plausible explanation for the failure of immune checkpoint inhibitor monotherapy for prostate cancer." (PMID 32552802, 2020).
systemic lupus erythematosus (26 papers, 2006 to 2025). An autoimmune multi-organ disease typically associated with vasculopathy and autoantibody production. "In humans, PD-1 also known as cluster of differentiation (CD279), human systemic lupus erythematosus (hSLE1) and systemic lupus erythematosus 2 (SLEB2) is encoded by the PDCD1 gene located at chromosome 2:241,849,881–241,858,908 reverse strand." (PMID 31075880, 2019). "Reduced RUNX1 binding caused by intronic SNPs has been proposed to cause aberrant regulation of PDCD1 (the programmed cell death 1 gene) in patients with systemic lupus erythematosus, and of SLC22A4 in patients with rheumatoid arthritis." (PMID 17786197, 2007). "PDCD1 (programmed cell death 1) has been reported to have a genetic association in systemic lupus erythematosus and rheumatoid arthritis in Caucasians." (PMID 17064404, 2006). "The association of polymorphisms in programmed cell death 1 (PDCD1) gene with systemic lupus erythematosus (SLE) risk is inconsistent across different studies." (PMID 28415570, 2017). "Allele and genotype frequencies of programmed cell death 1 (PDCD1) single nucleotide polymorphisms (SNPs) among systemic lupus erythematosus (SLE) patients and healthy controls." (PMID 25938972, 2015). "Recently, the PDCD1 (programmed cell death 1) gene polymorphism was reported to be associated with systemic lupus erythematosus (SLE), lupus nephritis and seronegative rheumatoid arthritis (RA)." (PMID 17064404, 2006). "PDCD1 knockout mice spontaneously developed lupus-like autoimmune symptoms, and immunoglobulin levels were significantly increased." (PMID 37644514, 2023). "In LN, the renal tissue of lupus mice and the serum of lupus patients exhibit atypically high levels of autophagy and autophagy markers, like programmed cell death-1 (Beclin-1)." (PMID 37894915, 2023). "Linkage analyses between the PDCD1 and lupus uncovered distinct patterns in different populations." (PMID 35047501, 2021). "Disruption of the PDCD-1 gene in C57BL/6 mice developed lupus-like glomerulonephritis." (PMID 28415570, 2017).
cutaneous melanoma (25 papers, 2015 to 2025). A primary melanoma arising from atypical melanocytes in the skin. "This study aims to analyze the association between the rs2227982 G>A, rs36084323 C>T, and rs7421861 A>G variants of the PDCD1 gene, as well as its gene expression, with cutaneous melanoma in patients from the western region of Mexico." (PMID 40869918, 2025). "Cutaneous melanoma, a fatal and aggressive tumor, has witnessed a transformative shift in its clinical management over the past decade with the advent of anti-programmed cell death 1 (PD1) and anti-cytotoxic-T-lymphocyte-associated antigen 4 (CTLA-4) immunotherapies, as well as targeted therapies." (PMID 38539531, 2024). "In recent years, immunotherapy have gained attention due to favourable results obtained with immunological checkpoint inhibitors targeting cytotoxic T lymphocyte- associated antigen 4 (CTLA-4), ipilimumab and programmed cell death-1 (PD-1) pembrolizumab, in the management of cutaneous melanoma." (PMID 31109147, 2019). "Our results indicated a significant abundance of macrophages in WT TIGIT skin melanomas (p = 0.008), as well as an enrichment of neutrophils in mutant PDCD1 skin melanomas (p = 0.007)." (PMID 39064019, 2024). "The key immune checkpoints including BTLA, CD86, CD244, and PDCD1 are recognized as predictors of sentinel lymph node metastasis in cutaneous melanoma." (PMID 35069935, 2022). "For example, PD-1 (encoded by PDCD1) and PD-L1 (encoded by CD274), a well-defined immunosuppressive axis in the TME, were found to be correlated with SPHK1 expression in most cancer types, including skin cutaneous melanoma (SKCM)." (PMID 36050478, 2022). "In addition, mRNA expression of PD-1 (PDCD1) was also elevated in metastasis cutaneous melanoma than that in primary cutaneous melanoma (P<0.0001)." (PMID 34326692, 2021). "Besides CTLA-4 blockade by ipilimumab, targeting new immune checkpoint inhibitory receptors and ligands such as programmed cell death 1 (PD-1) and programmed cell death ligand 1 (PD-L1) have evolved as further important targets in cutaneous melanoma." (PMID 25761109, 2015). "Therefore, this study aimed to evaluate the expression levels and genetic variability of PDCD1 in a well-characterized Mexican population diagnosed with cutaneous melanoma, integrating both genotypic and gene expression analyses with clinical and histopathological variables." (PMID 40869918, 2025). "In contrast, in skin cutaneous melanoma (SKCM), PDCD1 expression was found to be overexpressed in the tumor tissues as compared to the normal tissues." (PMID 40149458, 2025).
head and neck cancer (25 papers, 2017 to 2025). A primary or metastatic malignant neoplasm affecting the head and neck. "Immune checkpoint inhibitor therapy utilizing monoclonal antibodies directed against programmed cell death-1 (PD-1) and its ligand 1 (PD-L1) to target tumor-specific immune tolerance has become an established treatment modality for head and neck cancer patients with recurrent or metastatic HNSCC." (PMID 33921668, 2021). "For head and neck cancer including OSCC, treatment with anti-programmed cell death-1 (anti-PD-1) and anti-programmed cell death ligand-1 (anti-PD-L1) antibodies are crucial in the currently approved immunotherapy." (PMID 33763354, 2021).
metastatic disease (24 papers, 2019 to 2025). "Both PDCD1 (gene for PD-1) and CTLA4 are decreased in the recurrent/metastatic tumor compared to the primary tumor." (PMID 33796222, 2021).
myocarditis (23 papers, 2018 to 2026). Myocarditis is a condition that is characterized by inflammation of the heart muscle (myocardium). "The role of CD8+ T cells in immune checkpoint inhibitor–associated myocarditis (ICI-MC) has been addressed using a Pdcd1–/–Ctla4+/– mouse model that mimics human ICI-MC." (PMID 39817455, 2025). "In summary, this research not only establishes a reliable mouse model for studying ICIs-associated myocarditis but also highlights the significance of Ctla4 and Pdcd1 in the development of this adverse event." (PMID 38482205, 2024). "One of these is the mouse ICI-myocarditis model consisting of monoallelic loss of Ctla4 and complete deletion of Pdcd1 in C57BL/6 background." (PMID 36139654, 2022). "In contrast, MRL mice showed weak antibody production against cardiac myosin prompting that Pdcd1 deficiency might open the door for the development of myocarditis inclination in MRL mice." (PMID 39039301, 2025). "There is a notable rise in clonal cytotoxic Temra CD8+ cells, which exhibit distinct transcriptional alterations such as the upregulation of chemokines like CCL5, in both patients with ICIs-induced myocarditis and Pdcd1-/- mice with myocarditis." (PMID 38482205, 2024). "Adoptively transferring CD8+ T cells from Pdcd1–/– Ctla4+/– mice to Rag1–/– mice led to myocarditis development after two months, emphasizing the pivotal role of CD8+ T cells in fulminant myocarditis." (PMID 39465131, 2024). "Using the GSE213486 data series, we studied the heart tissues of four-week-old healthy C57BL6 mice and Pdcd1–/–Ctla4+/– mice with myocarditis (simulating dual PD1/CTLA-targeted anticancer therapy in clinical practice)." (PMID 37388276, 2023). "Subsequently, MRL mice with the PDCD1−/− genotype were shown to develop myocarditis instead of dilated cardiomyopathy." (PMID 36672615, 2023). "Mice with CTLA4 haploinsufficiency alone developed myocarditis, however of the mice with complete Pdcd1 knockout, approximately 50% of died within 3 months of age." (PMID 36263134, 2022). "Myocarditis cases have been reported in cancer patients after immunological therapy; for example, nivolumab treatment is a monoclonal antibody that blocks programmed cell death-1/programmed cell death ligand-1 ligand interaction." (PMID 32244307, 2020). "Fulminant myocarditis spontaneously develops in Pdcd1–/– Ctla4+/– mice." (PMID 39465131, 2024). "Clonal cytotoxic Temra CD8+ cells are increased in the blood of patients with ICI myocarditis, as well as in the blood/hearts of Pdcd1-/- mice with myocarditis, and these CD8+ cells are featured in some unique transcriptional changes, including the upregulation of several chemokines such as CCL5." (PMID 36354777, 2022). "Two groups reported independently that double deletion of Lag3 and Pdcd1 genes acts synergistically to cause lethal myocarditis while single deletion did not result in cardiac disease." (PMID 36139654, 2022). "Models with combined genetic knockout of Ctla4 and Pdcd1 showed that macrophages and CD8+ T-cells drive the myocarditis." (PMID 41598751, 2026).